RNU6-1317P (RNA, U6 small nuclear 1317, pseudogene)
Gene: Small nuclear RNA gene on chromosome 3 (175,767,558 to 175,767,661, forward strand). Ensembl gene ENSG00000201452.
Homologues: Orthologues: chimpanzee U6 (98% identical), macaque U6 (97% identical), rat LOC120099398 (80% identical). Paralogues in human: RNU6-35P (88% identical), RNU6-1316P (88% identical), RNU6-207P (88% identical), RNU6-25P (88% identical), RNU6-29P (88% identical), RNU6-492P (88% identical), RNU6-854P (88% identical), RNU6-1 (87% identical), RNU6-15P (87% identical), RNU6-19P (87% identical), RNU6-2 (87% identical), RNU6-20P (87% identical), and 1287 more.